SMARCB1 (SWI/SNF related BAF chromatin remodeling complex subunit B1)
Diseases named in the same sentence as SMARCB1 in open-access papers (continued):
Sharing a sentence is not in itself a finding about the gene and the disease.
tumor (continued). "Although the bioinformatic analysis did not elucidate the mechanism of SMARCB1 inactivation, it provided valuable exclusionary information and generated new hypotheses concerning the molecular drivers of this tumor." (PMID 41383551, 2025). "Interestingly, despite the substantial increase in tumor size detected by our mice model following SMARCB1 genetic silencing, lower SMARCB1 expression did not appear to impact the PFI of non-TKI-treated patients." (PMID 39971779, 2025). "In addition, enhancer of zeste homolog 2 (EZH2) inhibitors are new drugs for the treatment of cancers lacking SMARCB1, and preclinical studies have shown that they have the potential to modulate tumor immunogenicity and antitumor immune responses." (PMID 40115023, 2025). "However, TTI-101 treatment did not significantly affect the tumor growth in BCM-BL8091 (high SMARCB1) BLCA PDX model even after 77 days of treatment." (PMID 38355560, 2024). "Moreover, once-daily treatment with CP-C27 led to marked suppression of tumor growth in another SMARCB1-deficient JMU-RTK-2 xenograft model, but not in a SMARCB1-proficient H460 xenograft model." (PMID 38839769, 2024). "Immunohistochemical examination showed that the tumor cells were negative for SMARCB1." (PMID 38217014, 2024). "It has been hypothesized that the dual deficiency in key members of the SWI/SNF complex (e.g., SMARCA4 and SMARCA2, or SMARCB1 and SMARCA2) can induce dedifferentiation from a normal cell or a low-grade tumor into an aggressive high-grade tumor with small cell and/or rhabdoid features." (PMID 35200537, 2022). "These approaches, for example, do not consider that during the tumor transformation process, specifically when epigenetic modifiers such as Smarcb1 are altered, the transcriptome of a cell might be significantly changed, thus leading to wrong predictions." (PMID 35318328, 2022). "Samples from the SMARCB1 class could not be included in this part of the study due to insufficient quantities of available tumor tissue." (PMID 36443295, 2022). "Interestingly, SMARCB1 inactivation during slightly later embryonal stages (E12) did not lead to tumor formation." (PMID 34327198, 2021). "Thus, it appears that heterozygous loss of multiple genes residing in chromosome 22, including tumor suppressors, such as CHEK2, LZTR1 and SMARCB1, confers no proliferative advantage to the cells." (PMID 32724039, 2020). "No SMARCB1 protein is typically detectable in these tumor tissues." (PMID 31273213, 2019). "The tumor cells were completely negative for SMARCB1 protein expression by immunohistochemistry." (PMID 29625594, 2018). "The tumor was diagnosed by immunohistochemistry as a SMARCB1/INI negative AT/RT." (PMID 29779243, 2018). "Herein, we show that negative SMARCB1/INI1 expression (11% of CRCs) associates with loss of CDX2, poor differentiation, liver metastasis and shorter patients’ survival regardless of the MMR status or tumor stage." (PMID 24286138, 2013). "Three independent ChIP analyses each, on both F22 and STMpc rhabdoid tumor cell lines, showed that the CDKN1C promoter is acetylated in un-induced F22 and STMpc cells, however histone H3 acetylation increased 2 fold in both cell lines following SMARCB1 induction with 4HT." (PMID 19221586, 2009). "However, whether this sensitivity is due to the absence of SMARCB1 and whether the absence of SMARCB1 alters translation in rhabdoid tumor cells remained to be determined." (PMID 39542244, 2024). "Loss of function in the tumour suppressor gene SNF5 (also known as SMARCB1, INI1, and BAF47), a subunit of the SNF/SWI complex, results in unopposed EZH2 activity and increased H3K27me3 levels which drive tumour growth in the absence of EZH2 gain of function mutations [7••]." (PMID 33937922, 2021). "Tumor cells were positive for PAX8 and AMACR, while negative for CK7, 34BE12 and SF-1, and have retained SMARCB1 (INI-1), FH, SDHB and BRG-1 expression." (PMID 39996894, 2025).
tumor (continued). "Immunophenotypically, CDC typically expresses PAX8, 34βE12, and SMARCB1 (INI-1), and the tumor cells are typically negative for OCT3/4." (PMID 41294834, 2025). "Histopathological and immunohistochemical examination of the tumour revealed an ethmoid sinus locally invasive mass, poorly differentiated carcinoma and INI-1 (SMARCB1) negative." (PMID 39925590, 2025). "The tumor cells expressed SATB2, Bcl-2, TLE1, SMARCB1, but not CK, EMA, CD34, SMA, Desmin, S-100, CD99, STAT6, MyoD1, Myogenin, and Ki-67 LI is about 10%." (PMID 37361584, 2023). "SMARCB1 is part of the SWItch/sucrose non-fermentable (SWI/SNF) complex, which is involved in gene regulation and tumor development." (PMID 37450044, 2023). "This is reassuring since the majority of neoplasms that do not carry driver alterations within strong epigenomic modifiers (e.g., IDH1/2, SMARCB1) largely retain epigenomic features of their precursor lineages." (PMID 35158935, 2022). "We can hope that these trials will bring interesting and more homogeneous results, to better understand the role of SMARCB1 in tumor immunogenicity and optimize the use of ICI in patients with SMARCB1-negative diseases." (PMID 35327458, 2022). "While many of the identified transcription factors were described as central to cancer development (including SMARCB1, MAZ, EZH1 and H2AFX), none had an established role in ES, likely due to the limited number of functional studies of this tumor type." (PMID 34359637, 2021). "Histopathology staining of the primary tumor was consistent with RMC and had positive immunohistochemistry staining for CEA and negative staining for CK7 and INI‐1 (SNF5/SMARCB1)." (PMID 32259323, 2020). "Immunohistochemically (IHC), the tumor cells are positive for TFE3 and the renal tubular markers (PAX2 and PAX8), and completely negative for SMARCB1, an oncosuppressor protein." (PMID 27733182, 2016). "Analysis of this second tumor under central pathology review board concluded for the diagnosis of ATRT, supported by negative SMARCB1/INI1 staining." (PMID 23510391, 2013). "Additionally, in this case, the tumor cells showed Ki67<5%, and did not express CD117, TFE3, HMB45, or SDHB, while expressing FH and INI1(SMARCB1)." (PMID 41306531, 2025). "Immunohistochemistry (IHC) revealed tumor cells negative for AE1/AE3, PAX8, OCT4, CD34, SALL4, chromogranin, synaptophysin, NGFR CD20, WT1, cyclin D1, and SATB2, with lost expression of BRM (SMARCA2) and retained expression of INI1 (SMARCB1) and BRG (SMARCA4)." (PMID 39726498, 2024). "The SMARCB1/INI1 gene codes a subunit of the switch/sucrose non-fermentable (SWI/SNF) complex, actin-dependent chromatin remodeling complex and is known to act as a tumor suppressor." (PMID 34777208, 2021). "That SMARCB1 KD leads to elevated accessibility at CTCF binding sites is particularly noteworthy given recent findings that a SMARCB1-excluding non-canonical SWI/SNF complex (ncBAF, also termed GBAF) preferentially targets CTCF sites in mESCs and several tumor cell lines." (PMID 31033435, 2019). "Immunohistochemically, the tumor cells were diffusely positive for vimentin and CD99, focally positive for epithelial membrane antigen (EMA) and cytokeratin, but negative for SMARCB1/INI1." (PMID 29258531, 2017). "Similar to what reported for SMARCB1-negative MRT cells, restoration of SMARCB1 expression in SMARCB1-deleted ES cells (i.e., the VA-ES-BJ cell line) induces cell cycle arrest and impairs anchorage-independent growth and cell migration, substantiating its tumor suppressive role." (PMID 36078034, 2022).
cancer (309 papers, 2006 to 2026). A tumor composed of atypical neoplastic, often pleomorphic cells that invade other tissues. "Of 62 patients with INI1/SMARCB1 deleted/mutated epithelioid cancers, the ORR was 15% at data cut‐off, and an additional 26% exhibited disease control at 32 weeks of treatment." (PMID 40181550, 2026). "SMARCB1 deficiency occurs in up to 20% of human cancers; although the majority of SMARCB1 deficient tumors harbor homozygous loss of SMARCB1, numerous papers have reported a subset of these tumors exhibiting heterozygous deletions or extended 22q losses." (PMID 41317331, 2026). "Exploiting synthetic lethal interactions caused by specific mutations offers more promise, as in SMARCA4‐mutant cancers reliant on SMARCA2 or SMARCB1‐mutant tumors vulnerable to ncBAF‐targeting." (PMID 40181550, 2026). "Histologically, immunohistochemical analysis confirmed complete SMARCB1 or SMARCA4 loss (complete in carcinomas and partial in TCS), diffuse CK positivity, and high Ki-67 indices." (PMID 42074742, 2026). "Recently, we showed that treatment with simultaneous inhibitors of paralog pair CBP/p300 induces synthetic lethality in SMARCB1-deficient cancers." (PMID 39625239, 2025). "While the DMS screen used cell lines from three SMARCB1-deficient cancer contexts to ensure generalizability, subsequent functional assays were focused on the G401 model to study the effects of SMARCB1 re-expression." (PMID 40196006, 2025). "By establishing a high-throughput functional framework, this study offers a critical resource for elucidating SMARCB1’s mutational landscape and its implications for cancer diagnostics." (PMID 40196006, 2025). "The somatic mutation frequency of SMARCB1 is 0.92% across 239 cancer types, excluding MRTK, ATRT, and RMC, with 1,146 missense mutations observed." (PMID 40196006, 2025). "Our findings provide essential insights into SMARCB1’s mutational landscape and offer a valuable resource for further research into its role in cancer." (PMID 40196006, 2025). "SMARCB1 is also an important tumour suppressor gene and somatic SMARCB1 pathogenic variants (PVs) have been detected in ~ 5% of all human cancers." (PMID 40794298, 2025). "We found that only 12 missense mutations in SMARCB1 were classified as pathogenic or likely pathogenic, with two of these directly linked to cancer." (PMID 40196006, 2025). "Loss of SMARCB1 promotes cancer through various pathways, which will be described in more detail in this review." (PMID 40422882, 2025). "In 2024, a 14-year-old boy with an SMARCB1-deficient malignant tumor of the left orbit, staged T4N0M0." (PMID 41189975, 2025). "Mutations or loss of SMARCB1 can lead to uncontrolled cell growth and are associated with various cancers." (PMID 40003691, 2025). "SMARCB1 is a crucial tumor suppressor gene, and its deficiency is closely associated with the development of various malignant tumors." (PMID 40115023, 2025). "Astonishingly, 5% of all human cancers have pathogenic variants (PVs), albeit mostly somatic, in the SMARCB1 gene highlighting its general importance in tumorigenesis." (PMID 40794298, 2025). "It should be noted that the PVs in the SMARCB1 CTD are not only found in the germline of patients with CSS but are also observed as somatic variants in different types of cancer." (PMID 40794298, 2025). "Novel therapies, including immune checkpoint inhibitors, are under investigation, although their efficacy for SMARCB1-deficient carcinoma remains uncertain." (PMID 39925590, 2025). "Drug susceptibility screening using these inhibitors revealed that the CBP/p300 inhibitor A-485 was the most selective for SMARCB1-deficient cancers." (PMID 38839769, 2024). "Broader interrogation of the TCGA pan-cancer data (excluding BLCA) revealed that ~24% of tumors harbor deep or shallow deletions associated with low SMARCB1 mRNA expression." (PMID 38355560, 2024). "The rescue of SMARCB1 in SMARCB1-deficient cancer cells abrogates proliferation and promotes differentiation." (PMID 38390898, 2024).
cancer (continued). "This study underscores the necessity for personalized treatment strategies, including targeted therapies such as EZH2 inhibitors and immune checkpoint blockade, to address the unique molecular pathways in SMARCB1-deficient cancers." (PMID 39125735, 2024). "Tazemetostat, a specific EZH2 inhibitor, has been granted accelerated approval by the US FDA for the treatment of SMARCB1-deficient cancers." (PMID 39472584, 2024). "The most commonly accepted mechanistic insight into SMARCB1-deficient cancers is that the loss of the SMARC protein results in the pathological manifestation of cancer." (PMID 39125735, 2024). "Here, the authors report a paralog pair of CBP and p300 as a synthetic lethal target in SMARCB1-deficient cancers." (PMID 38839769, 2024). "There are now significant advances in the therapeutic targeting of SMARCB1-deficient cancers, gained through understanding of the molecular biology of this protein." (PMID 39125735, 2024). "Here, we identified a paralog pair, CBP/p300, as a promising therapeutic target for SMARCB1-deficient cancers." (PMID 38839769, 2024). "Further to this, a partial response to combination neoadjuvant Pembrolizumab and combination platinum doublet therapy has been reported in a case of advanced SMARCB1-deficient cancer." (PMID 39125735, 2024). "The discovery of biallelic, truncating mutations in the SMARCB1 (INI1, hSNF5, BAF47) gene in atypical teratoid/rhabdoid tumour (AT/RT), a particularly aggressive paediatric cancer, gave the first evidence of their role in carcinogenesis." (PMID 39471843, 2024). "Case reports of 3 patients with SMARCB1-loss aggressive pediatric cancers demonstrate evidence of response to immune checkpoint blockade." (PMID 38217014, 2024). "In initial research, individuals diagnosed with pediatric hypermutated and SMARCB1-deficient cancers have shown remarkable positive outcomes when treated with ICI therapies." (PMID 39204096, 2024). "Despite major advancements, effective treatment for patients with SMARCB1-deficient cancers has remained elusive." (PMID 38217014, 2024). "We thoroughly explore the mechanisms of ICIs, analyze their utilization in both adult and pediatric cancers, and investigate two potential avenues for advancing the use of ICIs in pediatric patients: hypermutated cancers and SMARCB1-deficient tumors." (PMID 39204096, 2024). "Here, we identify a paralog pair of CBP and p300 as a synthetic lethal target in SMARCB1-deficient cancers by using a dual siRNA screening method based on the “simultaneous inhibition of a paralog pair” concept." (PMID 38839769, 2024). "Mutation of SMARCB1 is implicated in several cancer types, such as malignant rhabdoid tumors and other aggressive cancers that primarily affect children." (PMID 39057032, 2024). "In particular, CP-C27 was more selective for SMARCB1-deficient cancer cells than A-485 or inobrodib." (PMID 38839769, 2024). "Modern advances in diagnostic techniques have occasionally identified SMARCB1 loss in tumors from multiple sites, broadly referred to as SMARCB1-deficient cancers." (PMID 38217014, 2024). "Loss of SMARCB1 has been identified as the sole mutation in a number of rare adult and pediatric cancers." (PMID 39125735, 2024). "Despite these major advancements, effective treatment for patients with SMARCB1-deficient cancers has remained elusive." (PMID 38217014, 2024). "Since most MRTs are SMARCB1-deficient, we aimed to compare cancer cells with ‘normal’ cells that express SMARCB1." (PMID 38893160, 2024). "In our study, we identified nine SMARCB1-deficient carcinomas, of which 77% were men and 23% were women, which is a similar distribution to previous case series reported." (PMID 39590317, 2024). "They should also consider SMARCA4 (BRG1)/SMARCB1-deficient carcinoma as a possible diagnosis to expand their diagnostic options." (PMID 38989233, 2024).
cancer (continued). "Specific treatments for SMARCB1-deficient tumors are now available for several carcinomas, and evaluating SMARCB1 deficits will become increasingly important." (PMID 39398818, 2024). "In the head and neck region, SMARCB1-deficient carcinomas are rare and mainly involve paranasal sinuses, especially sieve ones." (PMID 38989233, 2024). "Shared recurrent mutations in both NDD and cancer included those localized to the C-terminal domain of SMARCB1, the SMARCA4 N terminus, as well as within PBRM1 and ACTB subunits." (PMID 37500730, 2023). "BRD9 is essential for the proliferation of SMARCB1-deficient cancer cell lines and is therefore a therapeutic target for these lethal cancers, and it is also a key target for causing acute myeloid leukemia." (PMID 36733714, 2023). "In sum, inactivation of SMARCB1, a generally essential gene in cancer cells, is associated with lineage factor independence in ccRCC, but other mechanisms of lineage factor independence also exist." (PMID 37554444, 2023). "The efficacy of this treatment is being currently tested in other cancers having SMARCB1 or SMARCA4 mutations." (PMID 37093326, 2023). "The discovery of mutations in the SMARCB1 gene in rhabdoid tumors in 1998 was the first evidence linking the SWI/SNF complex to cancer." (PMID 37093326, 2023). "Studies in mouse models demonstrate that homozygous inactivation of SMARCB1 is embryonically lethal, although induced somatic homozygous loss results in the rapid onset of cancer in 100% of mice at 11 weeks." (PMID 37093326, 2023). "Immunohistochemistry is generally sufficient for diagnosis, although FISH or sequencing can be performed to demonstrate biallelic (homozygous) deletions of the SMARCB1 gene or loss-of-function (mostly truncating) mutations in SMARCA4-deficient carcinomas." (PMID 36941503, 2023). "Regarding SNCs with inactivation of one of the SWI/SNF complex genes, SMARCB1-deficient carcinoma was the most frequent subtype followed by SMARCA4-deficient tumors." (PMID 36937407, 2023). "The mSWI/SNF complexes were first linked to cancer in 1998 after O. Delattre and colleagues identified SMARCB1 biallelic inactivation as a driver of MRT." (PMID 35327458, 2022). "Since then, widespread sequencing efforts and the use of immunohistochemistry (IHC) have identified numerous other cancers with the depletion or loss of SMARCB1." (PMID 35892904, 2022). "Very rare ES associated with hereditary, cancer predisposing SMARCB1 alterations have been reported." (PMID 36078034, 2022). "Despite these major advancements, an effective treatment for patients with SMARCB1 deficient cancers has remained elusive." (PMID 35892904, 2022). "The SMARCB1 gene, located at 22q11.23, encodes a 47 kDa protein of four functional domains with frequent loss of function mutations in cancer." (PMID 35327458, 2022). "Extracranial malignant rhabdoid tumors (eMRTs) and RMCs were shown to have a rather low mutational burden, what indicates that SMARCB1 deficiency is the driver of these highly malignant tumors." (PMID 36291828, 2022). "The very few ongoing clinical trials which are recruiting very rare tumors including SMARCB1-deficient cancers (NCT02834013) and recurrent/metastatic HNSCC (NCT03370276) are now under way." (PMID 35805058, 2022). "Mechanistically, cancer-associated mutations in the C-terminal domain of SMARCB1 disrupt interactions with the nucleosome acidic patch and alter SWI/SNF binding genome-wide." (PMID 35323214, 2022). "In rhabdoid tumours, a highly malignant paediatric cancer, more than 95% of patients harbour a homozygous loss of the core subunit SMARCB1." (PMID 35456033, 2022). "These SMARCB1-deficient tumors have remarkably stable genomes, offering unique insights into the epigenetic mechanisms in cancer biology." (PMID 35892904, 2022). "These mutations contrast with the large deletions or truncations found in many other SMARCB1-deficient cancers." (PMID 35892904, 2022).